NGF (nerve growth factor)
Diseases named in the same sentence as NGF in open-access papers (continued):
Sharing a sentence is not in itself a finding about the gene and the disease.
diabetic neuropathy (continued). "Moreover, NGF supply in animal models of diabetic neuropathies reverses neuropathic signs by protecting the affected PNS neurons and normalizing their activity." (PMID 24244623, 2013). "Reduction of TRPV1 levels in nerve fibres in diabetic neuropathy skin may result from the known decrease of nerve growth factor (NGF) levels." (PMID 17521436, 2007). "Therefore, it remains unknown whether NGF is useful enough for predicting diabetic neuropathy and understanding its pathophysiology." (PMID 33669048, 2021). "Thus, the observed improvement in diabetic neuropathy may be mediated through the upregulation of NGF." (PMID 31031586, 2019). "Furthermore, NGF may have also prevented degeneration of peripheral nerves in clinical trials and experimental models of diabetic neuropathy." (PMID 31024320, 2019). "Therefore, induction of brain neurotrophins, sodium-potassium-ATPase activity and nerve growth factor (NGF) could be beneficial for the treatment or prevention of diabetic neuropathy." (PMID 27483315, 2016). "Recently, pathogenetic control of diabetic neuropathy has been improved after neurotrophic therapy, such as NGF treatment, and by targeting pathological factors, in both STZ-induced DM animal models and in the human condition, which could be relevant to diabetic hearing impairment." (PMID 25878713, 2015). "Gene expression analysis further demonstrated a significant upregulation of nerve growth factor (NGF) and a downregulation of brain Tyrosine Kinase Receptor A (TrkA) in individuals with diabetic neuropathy compared to healthy controls." (PMID 40687580, 2025). "In our study, we found that the mean level of NGF and BDNF of diabetic neuropathy animals decreased significantly (p < 0.05) compared to normal animals, while the treatment of NR showed the regeneration potential of NGF and BDNF in a dose-dependent manner." (PMID 36556476, 2022). "Cryopreserved human DPSCs (hDPSCs) ameliorate diabetic polyneuropathy, and the effects of hDPSC transplantation are related to VEGF and NGF secretion." (PMID 34572120, 2021). "NGF is known to control spinal SP and TRPV1, and it has been shown to be related to pain and diabetic neuropathy." (PMID 34445280, 2021). "The neurotrophins nerve growth factor (NGF) and brain-derived neurotrophic factor (BDNF) have been studied in diabetic neuropathy and chemotherapy-induced peripheral neuropathy (CIPN), with higher levels postulated to have a neuroprotective effect." (PMID 34661878, 2021). "DG can increase levels of the nerve growth factor (NGF) that are reduced in diabetic rats and enhanced nerve conduction velocities in a mouse model of diabetic neuropathy." (PMID 32215172, 2020). "Growth factors are generally implicated in the development of diabetic retinopathy (DR) and diabetic nephropathy (DN), while in diabetic neuropathy (DNU) some of them (such as VEGF, IGF-I and NGF) have a protective role." (PMID 24690397, 2014). "Diabetic polyneuropathy (DPN), characterized by early hyperalgesia and increased nerve growth factor (NGF), evolves in late irreversible neuropathic symptoms with reduced NGF support to sensory neurons." (PMID 23710226, 2013). "We have previously reported correlations of nerve growth factor (NGF), which regulates TRPV1 expression, with skin flare area in patients with diabetic neuropathy." (PMID 17683543, 2007). "In experimental models of diabetic neuropathies, NGF administration reversed the neurodegenerative signs and normalized the activity of neurons belonging to the Peripheral Nervous System." (PMID 27439311, 2016). "In addition, ALA seems to favour the production of nerve growth factor (NGF) and has been used in the treatment of diabetic neuropathy." (PMID 26034927, 2015).
diabetic neuropathy (continued). "Various growth factors such as insulin-like growth factor (IGF), nerve growth factor (NGF) and neurotrophin 3 (NT3) were found to be related to diabetic neuropathy: disruptions in their levels, especially NGF, could lead to disrupted regeneration of neurons and Schwann cells." (PMID 38540203, 2024). "Although there may be many cytokines which affect the therapeutic effects of hDPSC transplantation on diabetic polyneuropathy, we confirmed that the effect of hDPSC transplantation on MNCV and SNCV in diabetic mice was negated by human VEGF- and human NGF-neutralizing antibodies." (PMID 32546222, 2020). "There is some support for this hypothesis in painful diabetic neuropathy, where skin NGF levels are increased and systemic NGF antibodies reversed behavioural signs of neuropathic pain, but it is not known if this mechanism is specific to diabetic neuropathy." (PMID 24380503, 2014). "Phase I and phase II clinical trials of systemic administration of recombinant NGF reveal the safety and potential efficacy of this treatment for diabetic polyneuropathy, although a phase III trial showed no beneficial effects, possibly because the dosage and route of administration was suboptimal." (PMID 21037846, 2009). "NGF, IGF-I and ciliary neurotrophic factor (CNTF) are crucial players in the normal growth, maintenance and regeneration of the peripheral nervous system, but there is no such role for TGF-(1 in diabetic neuropathy." (PMID 24690397, 2014).
Parkinson disease (55 papers, 2006 to 2026). A progressive degenerative disorder of the central nervous system characterized by loss of dopamine producing neurons in the substantia nigra and the presence of Lewy bodies in the substantia nigra and locus coeruleus. "This underlines the therapeutic potential of the NGF for several neurological diseases, such as Parkinson’s or Alzheimer’s, as well as ocular disorders, such as corneal ulcers and macular degeneration and wound healing in pressure ulcers." (PMID 38791953, 2024). "It demonstrates significant therapeutic promise for neurodegenerative disorders, such as Alzheimer's and Parkinson's disease, primarily by stimulating the synthesis of nerve growth factor (NGF)." (PMID 41599268, 2026). "Serum growth factors (BDNF, FGF-21, NGF and proNGF), α-synuclein, physical performance and Parkinson’s Disease Fatigue Scale (PFS-16) responses were analyzed to evaluate the pre-post variation and differences among groups." (PMID 36845654, 2023). "In another study, NGF-adsorbed poly (butly cyanoacrylate) (PBCA) nanoparticles used for the treatment of Parkinson’s disease were created." (PMID 36365243, 2022). "Some studies suggest upregulation of NGF mRNA in astrocytes in models of traumatic injury, Parkinson’s disease (PD), and neuroinflammation." (PMID 35563321, 2022). "Subsequently, the use of NGF was put forward to treat a broader spectrum of neurological conditions affecting the central nervous system, such as Parkinson’s disease, degenerative retinopathies, severe brain traumas and neurodevelopmental dysfunctions." (PMID 34867367, 2021). "TRIB3 induction also occurs in response to neurotrophic factor (NGF) deprivation, Parkinson’s disease, and metabolic stress." (PMID 31191318, 2019). "Many signaling pathways including 14-3-3 mediated, neuregulin, semaphorin, ephrin, gap-junction, axonal guidance, as well as different growth factor signaling like EGF/EGFR, FGF, and NGF, were found enriched in Parkinson's disease pathology." (PMID 24688734, 2013). "In brain tissue of Parkinson's disease patients, GDNF, NGF, and brain-derived neurotrophic factor (BDNF) are deficient, hence the clinical trials of therapeutic GDNF injection into the brain of Parkinson's patients." (PMID 24023412, 2013). "Additionally, WB-EMS training has been shown to modulate serum proteins such as BDNF and nerve growth factor (NGF) in Parkinson’s disease patients." (PMID 39584899, 2024). "Moreover, C16 has shown a beneficial effect on the ALS/Parkinsonism dementia complex (PDC), representing symptoms analogous to AD’s such as dementia and Parkinsonism, when administrated along with angiopoietin 1, a nerve growth factor." (PMID 36671492, 2023). "These compounds can pass the BBB due to their low molecular weight which may beneficially impact on Alzheimer’s and Parkinson’s disease due to their impact on nerve growth factor (NGF)." (PMID 35330292, 2022). "For example, PS‐80 coated PBCA nanoparticles loaded with nerve growth factor were administered in a drug‐induced Parkinson's disease rat model, and a reduction in Parkinson's symptoms such as orientation‐research reaction, rigidity and tremor, and locomotor activity were observed." (PMID 34026447, 2021). "The chemical constituents from H. erinaceus can stimulate NGF-mediated neurite outgrowth, while Erinacine A can act as an anti-neuroinflammatory agent that confers neuroprotection in Parkinson’s disease rat model." (PMID 28553224, 2017). "Clinical experiences with NGF suggest that neurotrophins or compounds with neurotrophin-like actions might be useful to develop new strategies to treat Parkinson's disease (PD) and/or other neurodegenerative disorders." (PMID 24599318, 2014). "The mushroom’s capacity to stimulate nerve growth factor (NGF) synthesis has highlighted its potential in preventing and managing neurodegenerative diseases, such as Alzheimer’s and Parkinson’s." (PMID 40284172, 2025).
Parkinson disease (continued). "The mushroom’s ability to promote nerve growth factor (NGF) production has demonstrated its promise for preventing and treating neurodegenerative disorders such as Alzheimer’s and Parkinson’s diseases." (PMID 41157106, 2025). "In neuronal cells, nerve growth factor (NGF) withdrawal activates MLK3-JNK, which in turn mediates neuronal cell death and pathological neurodegenerative diseases, including Parkinson’s disease (PD)." (PMID 25874865, 2015). "Specifically, glial cell-derived neurotrophic factor (GDNF), nerve growth factor (NGF), and brain derived neurotrophic factor (BDNF) have been recognized as therapeutic trophic factors for Parkinson’s, Alzheimer’s and Huntington’s diseases, respectively." (PMID 24463293, 2014). "In Alzheimer’s and Parkinson’s diseases, the levels of brain-derived neurotrophic factor (BDNF), synaptophysin (SYN), and nerve growth factor (NGF) are reduced, leading to impaired synaptic plasticity as well as decreased neuronal density and cholinergic neuron survival in the hippocampus." (PMID 41375975, 2025). "Other long-lasting formulations for the treatment of Parkinson’s disease include PLGA microparticles (delivery of VEGF and GDNF), PLGA-collagen microparticles (delivery of GDNF fused with collagen binding peptide) and poly(butyl cyanoacrylate) nanoparticles (delivery of nerve growth factor, NGF)." (PMID 33096803, 2020). "Furthermore, the neurotrophic effects of NGF in experimental animal models of neurodegenerative conditions, like MPTP (Parkinson's disease), experimental allergic encephalomyelitis (multiple sclerosis), or ischemic retina degeneration mice support its potential as a promising neuroprotective agent." (PMID 21541365, 2011).
glaucoma (51 papers, 2008 to 2026). Increased pressure in the eyeball due to obstruction of the outflow of aqueous humor. "Expression profiles of endogenous NGF and its receptors are found to be altered in the retina and optic nerve in experimental glaucoma associated with RGC loss." (PMID 32099056, 2020). "Topical NGF application has previously been shown to be neuroprotective in glaucoma, with evidence of reduced RGC loss in experimental models and a suggestion of improved visual function in patients." (PMID 32099056, 2020). "Lambiase and coworkers reported that NGF eye drops reduced RGCs loss in glaucomatous rats and that topical NGF treatment in three patients with advanced glaucoma improved all parameters of visual function.." (PMID 28068360, 2017). "Even after discontinuing NGF therapy, neuronal function was maintained for 3 months signifying reduced risk of vision loss in advanced glaucoma." (PMID 24066234, 2013). "Several NTFs have been reported to be associated with glaucoma, including nerve growth factor (NGF), brain-derived neurotrophic factor (BDNF), ciliary neurotrophic factor (CNTF), fibroblast growth factor 2 (bFGF), glial-derived neurotrophic factor (GDNF), and neurturin." (PMID 36579616, 2022). "Interestingly, in a case-control study, serum BDNF and NGF levels were low in patients with early and moderate glaucoma, indicating that the NTFs have a potential to serve as diagnostic biomarkers for glaucoma." (PMID 35668928, 2022). "In fact, glaucoma progression could be related to neurotrophins deprivation; interestingly, low serum levels of BDNF and nerve growth factor (NGF) were associated to early moderate stages of glaucoma." (PMID 34366858, 2021). "The acute role of NGF and the glaucoma-associated proteins still needs further investigation and a specific gene knock-out mouse may serve this purpose." (PMID 25250333, 2014). "Nerve growth factor (NGF) helps in the healing and survival of ganglion cells, photoreceptors, and optic nerve after injury and has been implicated to have a role in pathophysiology of glaucoma." (PMID 18710547, 2008). "Furthermore, NGF treatments reduced the progressive loss of RGCs in a glaucoma model." (PMID 32218163, 2020). "Along with other strategies such as nicotinamide, recombinant human nerve growth factor, ciliary neurotrophic factor, and anticomplement C1q antibody, topical insulin has a strong scientific premise as a therapeutic for glaucoma." (PMID 41584099, 2026). "Using these techniques, multiple studies have uncovered the potential role of NTs in protecting RGCs during direct neurodegeneration, with BDNF and NGF delivery promoting RGC survival in models of experimental glaucoma." (PMID 39944766, 2025). "Recent studies have initiated the Phase I clinical testing of topical NGF drops for glaucoma, deeming its application safe and tolerable at high concentrations." (PMID 39944766, 2025). "The therapeutic potential of NGF has also been tested in neurotrophic keratitis, glaucoma, macular degeneration, retinitis pigmentosa, and pressure ulcers." (PMID 41210918, 2025). "Recombinant human NGF (rhNGF) eye drops were used in examining the safety, tolerability, and efficacy in patients with glaucoma." (PMID 39408817, 2024). "While for the use of neurotrophic factors, experimental evidence has proven the effectiveness of NGF treatment in degenerative diseases of the retina, such as glaucoma, retinitis pigmentosa, and diabetic retinopathy." (PMID 39473506, 2024). "It has been shown that in advanced glaucoma patients, topical treatment with NGF improved optic nerve functions, including visual acuity, visual field, and contrast sensitivity." (PMID 39458902, 2024). "NGF and PEDF are particularly interesting as these trophic factors have been individually investigated in clinical trials for retinal conditions, including NGF for retinitis pigmentosa, cystoid macular edema, and glaucoma, and PEDF for macular degeneration." (PMID 37443724, 2023).
glaucoma (continued). "Topically administered NGF rescued RGCs from degeneration and enhanced the visual function of individuals with advanced glaucoma." (PMID 35668928, 2022). "Various studies have revealed the beneficial effects of NGF and its use in glaucoma, corneal ulcers, human cutaneous ulcers, and retinal maculopathy." (PMID 36365192, 2022). "For glaucoma, other therapies have been proposed such as the use of recombinant human NGF (rhNGF) (ClinicalTrials.gov Identifier: NCT02855450)." (PMID 32218163, 2020). "Research has demonstrated that NGF protects RGCs against injury induced by ON transection, retinal ischemia-reperfusion, ischemic injury, and glaucoma." (PMID 33381196, 2020). "Recombinant NGF is in phase 1 clinical trials for glaucoma (Clinicaltrials.gov identifier: NCT02855450) after a previous clinical trial showed that topical delivery was well tolerated by patients." (PMID 33269115, 2020). "In a small study of patients with glaucoma, NGF eyedrops improved multiple aspects of visual acuity." (PMID 33269115, 2020). "Clinical studies suggest that the administration of NGF eye drops improves all parameters of visual function in patients with advanced glaucoma." (PMID 29098325, 2018). "Several studies indicate that NGF protects RGCs after ON ischemia or transection, ocular hypertension and glaucoma." (PMID 30524222, 2018). "The downregulation of NGF and NGF-receptor expression in the retina and ON is reduced by ocular application of NGF in a rat model of glaucoma and protects animals from neurodegeneration." (PMID 30524222, 2018). "It has been demonstrated that the injection of exogenous NGF protects retinal ganglion cells from degeneration and apoptosis in different experimental models of retinal detachment, diabetic retinopathy and glaucoma." (PMID 29098325, 2018). "We found that both BDNF and NGF levels were significantly reduced in glaucomatous sera and particularly in patients with early and moderate glaucoma compared to healthy controls." (PMID 28068360, 2017). "No information is currently available regarding the serum levels of NGF in glaucoma patients and their relationship with functional and morphological biomarkers of the disease." (PMID 28068360, 2017). "Serum levels of NGF in glaucoma patients were significantly lower than those measured in the healthy controls (4.1±1 pg/mL vs 5.5±1.2 pg/mL, p = 0.01)." (PMID 28068360, 2017). "mean, standard deviation and 95%CI for the mean of the differences between NGF serum levels of each glaucoma subgroup and healthy controls." (PMID 28068360, 2017). "Recently, applications of NGF as eye drops have been reported to protect retinal ganglion cells from degeneration in models of experimental glaucoma or DR." (PMID 27123463, 2016). "The beneficial effects of nerve growth factor (NGF) on the glaucoma have been recently suggested, but its effects on eye tissue are complex and controversial in various studies." (PMID 25250333, 2014). "Recent clinical trials of systemically and topically administrated NGF demonstrate that NGF is effective in treating several ocular diseases, including glaucoma." (PMID 25250333, 2014). "This review discusses the current understanding of the NGF signaling in retina and the therapeutic implications in the treatment of glaucoma." (PMID 25250333, 2014). "This review discussed current knowledge of glaucoma, with an emphasis on the NGF and NGF receptor(s) signaling pathways, and further explored the possibility of targeting the NGF signaling pathway as a strategy for the treatment of glaucoma." (PMID 25250333, 2014). "In three patients with advanced glaucoma, treatment with topical NGF produced an improvement in visual acuity, contrast sensitivity, and electrophysiological functions." (PMID 25250333, 2014). "In this review, we will examine the current understanding of the NGF signaling pathway and its potential as a therapeutic target for the treatment of glaucoma." (PMID 25250333, 2014).